SLC35A3 (solute carrier family 35 member A3)
Description:
Transports diphosphate-N-acetylglucosamine (UDP-GlcNAc) from the cytosol into the lumen of the Golgi apparatus, functioning as an antiporter that exchanges UDP-N-acetyl-alpha-D-glucosamine for UMP. May supply UDP-GlcNAc as substrate for Golgi-resident glycosyltransferases that generate highly branched, multiantennary complex N-glycans and keratan sulfate. However, the exact role of SLC35A3 still needs to be elucidated, it could be a member of a catalytically more efficient multiprotein complex rather than function independently as a single transporter.
Synonyms: AMRS
Tractability: Antibody: UniProt predicts a signal peptide or a membrane-spanning region. PROTAC: ubiquitination databases record sites on it; its protein half-life has been measured.
Gene: Protein-coding gene on chromosome 1 (99,969,351 to 100,035,634, forward strand). Ensembl gene ENSG00000117620.
Subcellular location: Golgi apparatus membrane
Pathways (Reactome):
Disease: Defective SLC35A3 causes arthrogryposis, mental retardation, and seizures (AMRS)
Transport of small molecules: Transport of nucleotide sugars
Gene Ontology:
Molecular function: protein binding; UDP-galactose transmembrane transporter activity; UDP-N-acetylglucosamine transmembrane transporter activity; pyrimidine nucleotide-sugar transmembrane transporter activity
Biological process: UDP-N-acetylglucosamine transmembrane transport; UDP-N-acetylglucosamine metabolic process; nucleobase-containing compound transport; organophosphate ester transport; pyrimidine nucleotide-sugar transmembrane transport; UDP-galactose transmembrane transport
Cellular component: Golgi membrane; Golgi apparatus; membrane
Genetic constraint (gnomAD): Loss-of-function variants: 10 observed, 15.23 expected, observed/expected ratio (o/e) 0.66, 90% interval 0.4 to 1.11. The upper end of that interval is the gene's LOEUF score, 1.11, which puts it in group 4 of 6, group 1 being the genes least tolerant of losing a copy. Missense variants: 115 observed, 153.38 expected, observed/expected ratio (o/e) 0.75, 90% interval 0.64 to 0.88. Synonymous variants: 44 observed, 54.34 expected, observed/expected ratio (o/e) 0.81, 90% interval 0.63 to 1.04.
Homologues: Orthologues: dog SLC35A3 (98% identical), pig SLC35A3 (98% identical), mouse Slc35a3 (95% identical), rat Mfsd14a (95% identical), tropical clawed frog slc35a3.2 (86% identical), tropical clawed frog slc35a3 (79% identical), guinea pig SLC35A3 (79% identical), zebrafish slc35a3a (78% identical), zebrafish slc35a3b (75% identical). Paralogues in human: SLC35A2 (52% identical), SLC35A1 (39% identical), SLC35A5 (28% identical), SLC35A4 (25% identical).
Diseases named in the same sentence as SLC35A3 in open-access papers:
SLC35A3 is named in the same sentence as 21 diseases in open-access papers, as found by Europe PMC text mining. Sharing a sentence is not in itself a finding about the gene and the disease. The quoted sentences say what the papers report.
breast carcinoma (3 papers, 2022 to 2025). "Previous studies have reported the important role of SLC35A3 in the development of T-cell lymphoblastic lymphoma, pancreatic cancer, and breast cancer, and it can serve as an early warning marker for these cancers." (PMID 38172565, 2024).
pancreatic cancer (2 papers, 2021 to 2024). "Seven GRGs: CDK1, DSC2, MET, PYGL, CHST12, ERO1A, and SLC35A3 were selected to construct the prognostic model related to the overall survival rate of patients with pancreatic cancer." (PMID 33912561, 2021). "CDK1, DSC2, ERO1A, MET, PYGL, and SLC35A3 were highly expressed while CHST12 was decreased in pancreatic cancer." (PMID 33912561, 2021). "Expression analysis further revealed that CDK1, DSC2, ERO1A, MET, PYGL, and SLC35A3 were highly expressed in pancreatic cancer while CHST12 was highly expressed in normal pancreatic tissues." (PMID 33912561, 2021).
arthrogryposis (1 paper, 2026). A rare, non-progressive congenital disorder characterized by multiple joint contractures which are present at birth. "In humans, biallelic mutations in SLC35A3 cause arthrogryposis, mental retardation, and seizures (AMRS)." (PMID 41751780, 2026).
cervical cancer (1 paper, 2022). A primary or metastatic malignant neoplasm involving the cervix. "In a recent study, a knockout of the SLC35A3 gene in human cervical cancer cell line HeLa enhanced cell spreading while suppressing cell migration and proliferation." (PMID 35892570, 2022).
colon adenocarcinoma (1 paper, 2024). "Compared to normal tissues, SLC35A3 mRNA expression was significantly decreased in colon adenocarcinoma (COAD) and rectal adenocarcinoma (READ)." (PMID 38172565, 2024).
colon cancer (1 paper, 2024). "Our analysis showed a significant decrease in the methylation levels of the SLC35A3 promoter in colon cancer and cancer, with statistical significance." (PMID 38172565, 2024). "Cell experiments demonstrated that elevated expression of SLC35A3 can inhibit the proliferation and invasion of colon cancer cells while promoting apoptosis." (PMID 38172565, 2024). "Compared to normal colon epithelial cells, colon cancer cells (SW620, HT29, HCT116) exhibited significant downregulation of SLC35A3 mRNA expression." (PMID 38172565, 2024). "qRT-PCR was used to detect the expression levels of SLC35A3 in human normal colon epithelial cell line NCM460 and human colon cancer cell lines HCT116, HT-29, and SW620." (PMID 38172565, 2024).
colorectal adenocarcinoma (1 paper, 2024). The most common type of colorectal carcinoma. "The analysis results showed that SLC35A3 was significantly downregulated in colorectal adenocarcinoma compared to normal tissues (p < 0.0001)." (PMID 38172565, 2024). "To further determine the differential expression of SLC35A3 between colorectal tumors and normal tissues, we analyzed the TCGA-COADREAD dataset, which included RNA sequencing data and clinical information from 647 colorectal adenocarcinoma tissues and 51 normal colon tissues." (PMID 38172565, 2024).
colorectal cancer (1 paper, 2024). A primary or metastatic malignant neoplasm that affects the colon or rectum. "We explored the mutation and promoter methylation level of SLC35A3 in colorectal cancer through databases to explore the potential pathogenesis of SLC35A3." (PMID 38172565, 2024). "The expression level of SLC35A3 is associated with the prognosis of many cancers, but its role in colorectal cancer (CRC) is unclear." (PMID 38172565, 2024). "The results of this study indicate that decreased expression of SLC35A3 is closely associated with poor prognosis and immune cell infiltration in colorectal cancer, and it can serve as a promising independent prognostic biomarker and potential therapeutic target." (PMID 38172565, 2024). "To further study the role of SLC35A3 in colorectal cancer cells, we overexpressed SLC35A3 using overexpression plasmids (OE-SLC35A3) in colorectal cancer cell lines HCT116 and SW620." (PMID 38172565, 2024). "We compared the methylation levels of the SLC35A3 promoter in colorectal cancer and adjacent normal tissues." (PMID 38172565, 2024). "In vitro experiments validated that SLC35A3 overexpression inhibit the proliferation and invasion ability of colorectal cancer cells, and promotion apoptosis of colorectal cancer cells." (PMID 38172565, 2024). "The clinical data of colorectal cancer patients from the KM-plotter database further verified that patients with high SLC35A3 expression had significantly better OS, RFS, and PPS than those with low SLC35A3 expression." (PMID 38172565, 2024). "In vitro experiments showed that overexpression of SLC35A3 inhibited the proliferation and invasion capability of colorectal cancer cells and promoted apoptosis." (PMID 38172565, 2024). "The UALCAN tool was used to analyze the promoter methylation level of SLC35A3 in colorectal cancer." (PMID 38172565, 2024). "In vitro experiments validated the function of SLC35A3 in colorectal cancer cells." (PMID 38172565, 2024). "We have conducted a comprehensive bioinformatics analysis to investigate the role of SLC35A3 in colorectal cancer (CRC), including its expression, clinical prognosis, diagnosis, genetic changes, promoter methylation, metabolic regulation, and immune cell infiltration." (PMID 38172565, 2024). "In order to understand the role of SLC35A3 in the development of colorectal cancer (CRC), we evaluated the expression level of SLC35A3 in tumor tissues and adjacent normal tissues of CRC based on the TCGA, GEO, ICGC, and HPA databases." (PMID 38172565, 2024).
depression (1 paper, 2017). "Thus, SLC35A3 may be associated with depression via its actions on Mgat5." (PMID 28596527, 2017).
pancreatic ductal carcinoma (1 paper, 2025). "Studies have indicated that SLC35A3 is aberrantly upregulated in pancreatic ductal carcinoma and affects glycolysis, which is also associated with patient prognosis." (PMID 40303483, 2025).
tumor (4 papers, 2021 to 2025). "SLC35A3 showed high expression in multiple tumor tissues but lower expression in some common cancers, such as colon, lung, and liver." (PMID 40303483, 2025). "These correlations suggest that SLC35A3 can recruit T-helper cells, Tcm cells, and Th2 cells to the tumor microenvironment and prevent the recruitment of Treg cells, which promote immune tolerance and angiogenesis." (PMID 38172565, 2024). "Considering that the tumor microenvironment plays an important role in tumor development, we also discussed the relationship between the expression of SLC35A3 and immune cell infiltration and immune checkpoints in CRC." (PMID 38172565, 2024). "Conversely, SLC35A3 displayed lower methylation levels in tumor tissues." (PMID 40303483, 2025). "Therefore, in order to describe the level of immune infiltration in CRC, we evaluated the potential impact of SLC35A3 on immune cell infiltration in the tumor microenvironment and the potential immune mechanisms mediated by SLC35A3." (PMID 38172565, 2024). "The expression levels of SLC35A3 in CRC were evaluated through tumor immune resource assessment (TIMER), The Cancer Genome Atlas (TCGA), Gene Expression Omnibus (GEO), International Cancer Genome Consortium (ICGC), Human Protein Atlas (HPA), qRT-PCR, and immunohistochemical evaluation." (PMID 38172565, 2024). "In contrast, the other family members, including SLC35A1, SLC35A3, SLC35A4, and SLC35A5, demonstrated lower expression in tumor tissues." (PMID 40303483, 2025). "The results showed that SLC35A3 mRNA and protein levels were decreased in CRC tumor tissues compared to adjacent normal tissues." (PMID 38172565, 2024). "Furthermore, our experimental validation confirmed the high expression of SLC35A3 in CRC tissue, which was positively correlated with the infiltration of helper T cells, suggesting its favorable impact on anti-tumor immune response in CRC patients." (PMID 38172565, 2024).
cancer (2 papers, 2024 to 2025). A tumor composed of atypical neoplastic, often pleomorphic cells that invade other tissues. "TIMER database analysis showed that the expression level of SLC35A3 mRNA varies in different types of cancer." (PMID 38172565, 2024). "TIMER database was used to determine the overall expression level of SLC35A3 in different types of malignant tumors." (PMID 38172565, 2024). "In addition, the WNT signaling pathway and cancer pathway were significantly enriched in the SLC35A3 low expression group in various cancer invasion features." (PMID 38172565, 2024). "The results showed that SLC35A3 had different expression patterns in various cancers." (PMID 38172565, 2024). "However, the DNA methylation level of SLC35A3 in CRC is lower than that in adjacent tissue, suggesting that some cancer-related transcriptional regulations may influence the gene expression of SLC35A3 during tumorigenesis." (PMID 40303483, 2025). "GSEA revealed that SLC35A3 may be involved in energy metabolism, DNA repair, and cancer pathways." (PMID 38172565, 2024). "Additionally, in the low-expression phenotype of SLC35A3, WNT signaling pathway, cancer pathways, and various invasive markers of cancer were significantly enriched, suggesting that SLC35A3 may play a role in regulating cancer signaling pathways, the occurrence and invasion of CRC." (PMID 38172565, 2024).
SLC35A3 also shares sentences with these, for which no sentence is quoted: asthma (1 paper); autism spectrum disorder (1); cholangiocarcinoma (1); chondrodysplasia (1); colorectal tumors (1); epilepsy (1); lung carcinoma (1); pancreatic adenocarcinoma (1); rectal adenocarcinoma (1).